FAP (fibroblast activation protein alpha)
Diseases named in the same sentence as FAP in open-access papers (continued):
Sharing a sentence is not in itself a finding about the gene and the disease.
tumor (continued). "The functional role of FAP and its co-expressing genes highlighted the tumor-promoting pathways such as focal adhesion, ECM receptor interaction, PI3K/Akt signaling and proteoglycans in cancer." (PMID 39579201, 2024). "FAP-positive CAFs inhibit T cell infiltration into the tumor through CXCL12, and depletion of these fibroblasts or targeting of CXCL12 increases the sensitivity to immune checkpoint blockade of PC in preclinical models." (PMID 38352864, 2024). "Due to its increased expression in the stroma of tumors and of metastases, and given the potential impact of the tumor stroma on treatment outcome, FAP was identified as a new and promising target for tumor detection and therapy." (PMID 37584717, 2024). "Of the various targets of PT-100, FAP exhibits enzymatic activity and can assist tumor cell infiltration and invasion by participating in the remodeling of intercellular substances." (PMID 38672409, 2024). "Encouragingly, 177Lu-FAP-2286 also showed considerable potential in tumor remission and inhibition, shedding new light on FAP-targeted peptide-based radionuclide therapy." (PMID 38543239, 2024). "The clinical implications of fibroblast activation protein (FAP)-positive CAFs (FAP+CAFs) were evaluated based on tumor specimens from NSCLC patients and bioinformatic analysis of online databases." (PMID 38459511, 2024). "As a critical contributor to fibroblast activation, FAP is specifically expressed in the tumor stroma, which has prominent clinical implications." (PMID 38459511, 2024). "Starting in 2022, terms like radiation-dosimetry, radionuclide therapy, volume delineation, tumor retention, and tumor-to-background ratio became popular, highlighting the growing interest in FAP-targeted radioligand therapy." (PMID 39758423, 2024). "This is of importance, since a meta-analysis evaluating histologic FAP expression in various tumors showed significant correlation between high FAP expression of tumors and tumor progression as well as overall survival." (PMID 37584717, 2024). "A PDAC PDX, PDX2494, revealed positive staining for both α-smooth muscle actin and FAP in the tumor microenvironment, with about 9% of the total tumor area positive for FAP." (PMID 39266288, 2024). "The fusion of an anti-FAP antibody to IL2v allows for increased localized IL2v exposure in FAP-positive tissues in the tumor microenvironment; however, free or unbound FAP-IL2v can still bind to IL2Rβγ in other tissues, causing IL2-related adverse effects." (PMID 39140264, 2024). "In this study, we analyzed FAP expression in 1,216 tumor samples across 23 tumor types and 70 subclassifications." (PMID 38558814, 2024). "FAP inhibitors, such as sibrotuzumab, aim to target FAP expressed by CAFs, reducing their tumor-promoting activity." (PMID 39600368, 2024). "The pioneering clinical study involving FAP-targeting radiopharmaceuticals utilized 131I-labeled mAbF19 for tumor imaging in patients with liver metastases from colon cancer." (PMID 38543239, 2024). "Due to their broad applicability and highly specific tumor uptake, FAP-targeting molecules are being investigated as theranostic agents in various tumors." (PMID 39008063, 2024). "One reason is that FAP-CAR T cells were reported to fail to regulate tumor growth, and induce on-target off-tumor toxicity (OTOT), including lethal osteotoxicity and cachexia." (PMID 39086477, 2024). "Many of these strategies target the fibroblast activation protein (FAP), which is almost exclusively expressed on CAFs, although FAP-expression by fibroblasts in inflammatory disease and by some types of tumor cells is also reported." (PMID 39073475, 2024). "FAP promotes tumor growth by promoting angiogenesis and ECM remodeling and facilitates the progression of tumors by suppressing the anti-cancer immune response." (PMID 38275890, 2024).
tumor (continued). "High FAP expression has been correlated to higher tumor grade, high recurrence rates, and poor survival across a wide range of human cancers, including breast, oral squamous cell carcinoma, gastric, renal, colorectal, lung, ovarian, pancreatic, and melanoma." (PMID 38275890, 2024). "The FAP-CAR T cells has been reported to inhibit tumor progression in an immune-response dependent manner in several tumor models." (PMID 39086477, 2024). "In our analysis, we found 4 distinct CAF subtypes expressing FAP (CAFs 9, 10, 11 and 14): among this, CAFs 10 and 11 were the only CAF subtypes significantly enriched in tumor-stroma interface region and strictly associated to tumor cells." (PMID 39575252, 2024). "Although some of these novel FAP-targeting compounds demonstrated durable tumor accumulation (e.g., OncoFAP), the modifications have not significantly improved the tumor retention time." (PMID 39073475, 2024). "As an extensively explored target, especially in conjunction with positron emission tomography/computerized tomography (PET/CT), various strategies including small molecules, peptides, and antibodies have emerged to harness FAP for tumor imaging and treatment." (PMID 38543239, 2024). "The results showed that, after the Secukinumab administration, the volume of the subcutaneous tumor was smaller and the weight of the tumor was lighter in either FAP-OE or IL-17-OE models." (PMID 38740736, 2024). "On the one hand, the removal of FAP+ CAFs disrupts the dense matrix and stromal border around tumor clusters, thereby facilitating the trafficking of cytotoxic effector cells and their direct communication with cancer cells." (PMID 39107856, 2024). "Another widely used marker for CAFs in various tumor types is fibroblast activation protein alpha (FAPα), and its expression is correlated with PNI and poor prognosis." (PMID 37610689, 2024). "Research has demonstrated that CAR-T cells targeting stromal cells expressing FAP effectively inhibited tumor growth in mouse models of solid tumors." (PMID 38622705, 2024). "Fibroblast activation protein-α (FAP), is highly expressed in CAFs within various tumor tissues, and is considered a crucial molecule engaging in TME remodeling and tumor evolution." (PMID 39174509, 2024). "Compared with U87MG xenografts, PDX2494 demonstrated lower tumor uptake, which correlates with its lower percentage of FAP-positive tumor area (9% vs. >40%)." (PMID 39266288, 2024). "Then obtained cancer-derived exosomes with the expression of FAP antigen that can target CAFs to exert anti-tumor effects." (PMID 38644492, 2024). "Fibroblast activation protein (FAP), overexpressed on CAFs, is considered a universal tumor-targeting antigen." (PMID 38690275, 2024). "Overexpression of FAP has been reported to induce tumor cell proliferation, migration, and invasion." (PMID 38826849, 2024). "Clinical correlation analysis revealed that high infiltration of FAP+ CAFs correlated with tumor progression and reduced OS." (PMID 39239526, 2024). "IL-2v has been fused with several mAbs targeting PD-1, carcinoembryonic antigen (CEA), and fibroblast activation protein alpha (FAP), effectively targeting PD-1+ T cells, tumor cells, and cancer-associated fibroblasts, respectively." (PMID 39595576, 2024). "We also proved the utility of [18F]FAPI-74 in PET imaging, with immunostaining confirming FAP expression in MDA-MB-231 tumor cells." (PMID 39519118, 2024). "Studies have revealed the relevance of FAP with higher tumour grade, metastasis and worse overall survival, such as in breast invasive ductal carcinoma, colon cancer and gastric cancer." (PMID 38158643, 2024). "Compared with that in the control group, there was a heightened accumulation of [89Zr]Zr-B12 IgG in FAP-positive tumor cells." (PMID 38543239, 2024).
tumor (continued). "Conclusive in vivo experiments in mice further corroborated that the ratio of tumor-to-organ uptake pertaining to 177Lu-labeled FAP mAbs ESC11 and ESC14 surpassed that of their first-generation radionuclide-labeled FAP-targeted antibodies." (PMID 38543239, 2024). "Like its analog FAPI-02, FAPI-04 exhibited rapid internalization into FAP-positive tumors and fast renal clearance of its unbound fraction, leading to swift accumulation at tumor sites." (PMID 39765634, 2024). "FAP actively supports the proliferation, migration, and invasion of tumors, endothelial cells, and immune cells, contributing to tumor invasiveness, neovascularization, and immune evasion." (PMID 40337455, 2024). "Cancer-associated fibroblasts induce the cancer phenotype, account for 90% of the macroscopic tumor mass, and strongly express FAP in >90% of carcinomas." (PMID 38334567, 2024). "As such, further work is needed to assess FAP expression by IHC and tumor uptake at FAPI PET imaging across a range of benign and malignant liver lesions." (PMID 39664608, 2024). "Even though these xenografts can demonstrate resemblance to a patient’s tumor, the FAP expression in healthy organs remains different between mice and man, especially due to the higher levels of soluble FAP in mice." (PMID 39718718, 2024). "VbP was initially thought to inhibit fibroblast activation protein (FAP), leading to reduced tumor growth in fibrosarcoma, lymphoma, melanoma, and mastocytoma-derived syngeneic-tumor models." (PMID 38391959, 2024). "Because of its activity, eNVs–FAP-engineered ASC Exos represent a special candidate as a tumor vaccine to be used for our second T.A.E. component to locally target the tumor parenchyma cells and the surrounding cellular environment." (PMID 38607053, 2024). "This suggests FAP’s role in forming tumor blood vessels and remodeling the surrounding matrix, potentially affecting tumor growth and spread." (PMID 39035007, 2024). "Due to its abundant presence within the tumor mesenchyme, FAP can serve as a target for radionuclide antibody conjugates in cancer patients." (PMID 38543239, 2024). "The introduction of FAP-targeted CAR-T cells has been observed to reduce tumor blood supply and halt tumor growth." (PMID 38693104, 2024). "Activated CAFs express fibroblast activation protein (FAP), a type II transmembrane cell surface proteinase, which is profoundly activated during tissue remodeling, tumor growth, and inflammatory disorders." (PMID 39766079, 2024). "Recently, we described the development of scFv- and IgG-based novel TMs for redirection of UniCAR T-cells to FAP, a marker of the tumor microenvironment (TME)." (PMID 39000348, 2024). "As expected, the NT‐T cells generally secreted only low levels of these factors, even in the presence of FAP+ GNS tumor cells." (PMID 38975278, 2024). "Due to the significant increase in FAP marker expression in fibroblast cells of tumor tissue compared to normal tissue, it seems that FAP can be used as a very good therapeutic marker, especially in patients with high levels of CAF cells." (PMID 39030445, 2024). "In recent years, radiotracers targeting TATE or FAP have been extensively studied for tumor imaging, with some already in clinical use." (PMID 39770488, 2024). "Of the synthesized FAP molecules, FAP-2286 was identified as a promising tracer for clinical Phase I studies because FAP-2286 maintained higher tumor selectivity and efficacy in comparison to FAPI-46 in pre-clinical models." (PMID 39598580, 2024). "Anti-FAP NIR-PIT effectively depleted FAP+ CAFs, as well as FAP+ myeloid cells, and suppressed tumor growth, whereas anti-podoplanin NIR-PIT was ineffective." (PMID 38275890, 2024). "Although tumor progression by FAP-targeted NIR-PIT was strongly suppressed after only a single treatment, more intense treatment is needed to achieve complete remission in these models." (PMID 38555315, 2024).
tumor (continued). "The use of the FAP-targeting inhibitor (FAPI), small ligand (oncoFAP), and cyclic peptide (FAP-2286) has achieved impressive results in tumor diagnosis." (PMID 38176714, 2024). "In the context of immune infiltration, FAP expression negatively correlated with CD8+ T-cell infiltration in five tumor types and positively with regulatory T-cell infiltration in four tumor types." (PMID 39055892, 2024). "Therapeutic approaches target FAP by inhibiting enzymatic function or introducing antibodies and immunotherapies into the tumour microenvironment." (PMID 38397199, 2024). "Specifically, ligand-receptor interactions between FAP+ CAFs and tumor cells and endothelial cells in ICC were investigated." (PMID 39239526, 2024). "The comprehensive evaluation of FAP across tumors identified it to be specifically expressed in tumor samples when compared to normal samples." (PMID 39579201, 2024). "This has opened the door for FAP-inhibitor development for tumor-specific targeting small molecule inhibitors and radiopharmaceuticals." (PMID 39664608, 2024). "Efficacy of [225Ac]Ac-FAPI-46 and/or ICB was further compared in FAP-overexpressing FSA (FSA-F) tumors that were sensitive to ICB or rendered ICB-resistant by tumor-induction in the presence of Abatacept." (PMID 39008063, 2024). "Because of PDX2494’s low FAP expression, high activity was administered with corresponding low tumor MAD and penalizing kidney MAD for the conventional and pretargeting high cohorts." (PMID 39266288, 2024). "Within the tumor bed, we were able to distinguish these FAP+ CAF clusters from cancer cells by detecting genomic alterations." (PMID 38561380, 2024). "Following digital analysis, we divided the patient cohort according to median expression in tumor stroma (FAP: n = 106 low, n = 105 high; PDGFRb: n = 106 low, n = 106 high; periostin: n = 106 low, n = 105 high; α-SMA: n = 107 low, n = 106 high)." (PMID 38328551, 2024). "FAP staining within tumor specimens primarily localized in the stromal component adjacent to tumor cells." (PMID 38558814, 2024). "FAP expression in the tumor microenvironment was validated in a PDAC PDX model with both immunohistochemistry and PET/CT imaging." (PMID 39266288, 2024). "In conclusion, we demonstrate that FAP-targeted NIR-PIT improved anti-tumor immunity in a CAF-rich tumor model, by selective killing FAP+ CAFs and activating an immune response." (PMID 38555315, 2024). "The fibroblast activation protein (FAP) is a membrane-bound serine protease that is expressed by activated fibroblasts and other cell types in the tumor microenvironment." (PMID 38505595, 2024). "This species-cross reactivity allows us to utilize mice model to somewhat predict clinical on-target off-tumor toxicity (OTOT) of the FAP-CAR T cells in the treatment of solid tumors." (PMID 39086477, 2024). "Cancer-associated fibroblast (CAF) cells in the tumor were labeled using α-smooth muscle actin (α-SMA) (green signal) and fibroblast activation protein (FAP) (yellow signal)." (PMID 38693181, 2024). "Histologically, the MMTV-PyVT tumors also had a high prevalence of α-SMA+FAP+ cells at the tumor periphery." (PMID 38275890, 2024). "The establishment of a single and robust method across varying tumor and specimen types presents a pivotal advancement in the systematic assessment of FAP (Fibroblast Activation Protein) rule in TME." (PMID 38558814, 2024). "FAP-2286 was developed to increase the biological half-life, hoping to slow the washout from target tissue, and increase the radiation dose to the tumor." (PMID 39065684, 2024). "Overall, FAP+ CAFs are enriched in tumor samples, particularly at HCC borders, and exhibit significant interaction potential with macrophages." (PMID 39239526, 2024). "Fibroblast activation protein (FAP) is expressed in the tumor microenvironment (TME) of various cancers." (PMID 38575990, 2024).
tumor (continued). "FAP is expressed in a wide range of tumor types, making it a promising target for cancer imaging and radionuclide therapy in recent years." (PMID 38176714, 2024). "Only when the immune checkpoint therapy was coupled with inhibition of FAP+ CAF-secreted CXCL12 the anti-tumor effect was observed." (PMID 38455762, 2024). "Previous studies have shown the importance of piperazine-based linkers for maintaining the good tumor uptake of FAP-targeted tracers." (PMID 38398552, 2024). "For tumor detection, among 44 patients requiring staging, [68Ga]Ga-FAP-2286 detected all primary tumors across nine different cancer types, whereas [18F]FDG missed nine tumors." (PMID 39765634, 2024). "Although the absolute 177Lu uptake at 24 and 72 h was increased in the tumor with FAP-2286, the tumor-to-kidney ratio was better for FAPI-46 at 3 h (21.0 vs. 9.6), identical at 24 h (12.7 vs. 13.1), and better for FAP-2286 at 72 h (27.3 vs. 8.18)." (PMID 39065684, 2024). "In contrast, FAP+ fibroblasts were least frequent at tumor zone and increased in count closer to the TME compartment." (PMID 38951801, 2024). "IHC staining of CAF marker FAP showed that the FAP-positive cells from tumor lesion were significantly increased and had a stronger staining compared to the dermis of patch lesion in the same patients." (PMID 39963655, 2024). "Of note, FAP-targeted radiopharmaceutical therapy is a possible therapeutic option and has shown promising results in other tumor entities." (PMID 39477500, 2024). "In head and neck cancers (HNCs), fibroblast activation protein (FAP) is expressed by CAFs within the tumor microenvironment." (PMID 39588373, 2024). "Homodimeric FAP inhibitors have been reported to exhibit high FAP affinity, significant tumor uptake, prolonged tumor retention, and reduced accumulation in other organs, making them valuable for both diagnosis and therapy." (PMID 39519118, 2024). "The tumor-specific expression patterns evidenced in FAP were further supported by the differential expression observed between the tumor and normal tissues of various cancers." (PMID 39579201, 2024). "FAP expression in FSA tumors was quantified using [68Ga]Ga-FAPI-46 PET/CT 11–19 days after tumor cell inoculation." (PMID 39008063, 2024). "Immunohistochemistry revealed an FAP-positive tumor area of more than 40% in U87MG subcutaneous xenografts." (PMID 39266288, 2024). "CAFs, identified based on the expression of fibroblast-associated markers such as FAP, CD90, and PDGFRβ, play a central role in influencing the tumor immune response." (PMID 39834587, 2024). "Of note, FAP+ HO-1+ TAMs were predominantly located in the perivascular region of tumors and supported trans-endothelial tumor cells migration and metastatic spread." (PMID 39611159, 2024). "These FAP-specific radiotracers have demonstrated excellent tumor detection properties compared to traditional radiopharmaceuticals such as [18F]FDG, especially in cancers with low metabolic activity, like liver and biliary tract tumors." (PMID 39765634, 2024). "Fibroblast-activated protein (FAP) expression in glial cells is attributed to FAP-positive foci on tumor vessels and neoplastic cells." (PMID 39759219, 2024). "After searching the TCGA database, we found that the expression of FAP was higher in tumor tissues than in normal tissues." (PMID 38740736, 2024). "68Ga-FAPI and 18F-FAPI are among the many FAP-targeting radiotracers developed that play a significant role in tumor detection." (PMID 39272726, 2024). "The brown DAB staining, which marks FAP-positive areas, was visible across the tumor cells, with additional staining detected in the stromal regions." (PMID 39335703, 2024). "In CRC tumor tissue, FAP is mainly expressed by CAFs, and the amount and activity of CAFs largely determine the expression of FAP." (PMID 39376651, 2024). "This leads us to understand that CAFs subpopulation with increase FAP expression promotes higher tumor aggressiveness and immunosuppression." (PMID 38606999, 2024).